FTH1P16 (ferritin heavy chain 1 pseudogene 16)
Synonyms: formerly FTH2; FTHL16
Gene: Processed pseudogene on chromosome 11 (77,734,475 to 77,735,026, reverse strand). Ensembl gene ENSG00000227376.
Diseases named in the same sentence as FTH1P16 in open-access papers:
FTH1P16 is named in the same sentence as 1 disease in open-access papers, as found by Europe PMC text mining. Sharing a sentence is not in itself a finding about the gene and the disease. The quoted sentences say what the papers report.
prostate carcinoma (2 papers, 2019 to 2020). A carcinoma that arises from epithelial cells of the prostate gland. "In DU145 and PC3 models of prostate cancer FTH1 and FTH1P11 and FTH1P16 show near equimolar expression level, further underlining the fulfilment of an important criterion for an effective parental gene:pseudogene ceRNA network." (PMID 33260500, 2020). "The FTH1 query also resulted in the identification of pseudogenes (FTH1P2, FTH1P8, FTH1P11, FTH1P16) that regulate FTH1 in prostate cancer as well novel miRNAs that may be involved in ceRNA network regulation of FTH1 in prostate cancer." (PMID 31029062, 2019). "Interestingly, in DU145 and PC3 models of prostate cancer, the addition of iron induced the expression not only of FTH1, but also of FTH1P11 and FTH1P16, two pseudogenes whose expression is not regulated by IREs, while iron depletion down-regulated FTH1, FTH1P11, and FTH1P16." (PMID 33260500, 2020).